RB1 (RB transcriptional corepressor 1)
Diseases named in the same sentence as RB1 in open-access papers (continued):
Sharing a sentence is not in itself a finding about the gene and the disease.
tumor (continued). "NcRNA-RB1 (a lncRNA expressed in the RB1 promoter) suppresses the expression of calreticulin, which is a calcium-binding chaperone and affects the presentation of antigen to cytotoxic T cells, and prevents tumor cells release “killing me” signal." (PMID 35606755, 2022). "Due to lack of material and models, the understanding of RB1 mutations in tumor development is still unsatisfactory." (PMID 35565295, 2022). "However, the protein expression of RB1 in ovarian tissues was higher than that in other normal organs and tumor tissues." (PMID 35299734, 2022). "Furthermore, ablation of BECN1 inhibits xenograft tumor growth through elevated RB expression and reduced autophagy, while simultaneous silencing of RB1 restores tumor growth but has little effect on autophagy." (PMID 36230664, 2022). "Similarly, we found that deletion of the RB1-S region abolished EZH2 binding at the RB1 promoter in RB1-S-deleted cells compared to wild-type tumor cells (second panel, lane 2)." (PMID 36175480, 2022). "RB1 mutation could be detected in 8 cases among 13 LCNECs in our cohorts, and 5 of 11 LCNEC-null tumours showed RB1 alteration." (PMID 35144629, 2022). "For example, RB1 (retinoblastoma-associated protein) at S807, which could promote cell cycle progression in cancer cells, YAP1 at S109, which has been reported associated with tumor metastasis, was significantly overexpressed in tumor tissues." (PMID 36434634, 2022). "It is a tumor suppressor and works with Rb1 to halt G1 to S phase transition." (PMID 35538578, 2022). "This observational data is consistent with the notion that pocket protein paralogues have partially overlapping tumor suppressor functions, likely based on their overlapping role in cell cycle control, but that RB1 has a more dominant and unique role in tumor suppression." (PMID 35368709, 2022). "Intriguingly, a sixth tumor (15R) also showed partial loss of pRb expression without a detectable underlying genetic alteration in RB1, suggesting alternative mechanisms that regulate RB1 gene expression." (PMID 36071033, 2022). "Piezo1 could also upregulate the expression of histone deacetylase 2 (HDAC2), which suppresses Rb1 via epigenetic silencing, thereby expanding MDSCs and conferring a tumor immunosuppressive microenvironment." (PMID 36230880, 2022).
tumor (continued). "The effects of miR‐192‐5p/RB1 on Tregs were further explored with an established tumour model." (PMID 35969010, 2022). "So as the main mechanism underlying G1-targeted CDK4/6 inhibitors go through avoiding RB1 tumor suppressor phosphorylation and its subsequent inactivation, the effects of some agents such as palbociclib require the presence of a functional pRb protein to work properly." (PMID 35681689, 2022). "This emphasizes RB1’s unique tumor suppressor activity in the lung." (PMID 35368709, 2022). "We found that miR‐192‐5p/RB1 promoted the PDL1 expression on tumour cells and increased the percentage of PD‐1+FOXP3+ Tregs, which may enhance the immunosuppressive capacity of Tregs and promote immune evasion in GC." (PMID 35969010, 2022). "Indeed, alteration of the RB1 pathway in mice leads to increases in tumor formation, particularly after exposure to chemical carcinogens and radiation." (PMID 34983823, 2022). "In summary, we revealed that miR‐192‐5p promotes GC EMT, thereby promoting malignancy and FOXP3+ Treg cell differentiation via RB1/NF‐κBp65/IL‐10 axis, thereby highlighting the miR‐192‐5p/RB1/NF‐κBp65/IL‐10 pathway as a new therapeutic strategy for tumour immunotherapy in GC." (PMID 35969010, 2022). "In addition, epigenetic deregulation of tumor-promoting pathways has been shown to be important for RB tumorigenesis and disease progression beyond RB1 inactivation." (PMID 36130950, 2022). "In addition to tumor development, RB is also important for normal fetal development as homozygous Rb1 mutations are embryonically lethal in mice." (PMID 35361964, 2022). "In RB1-deficient MDA-MB-436 breast xenografts, OXPHOS is highly upregulated and can be inhibited by the mitochondrial translation inhibitor tigecycline, which ultimately strongly impairs tumor growth." (PMID 34976949, 2021). "RB1 may be regarded as the prototype tumor-suppressor gene with high penetrance in a specific age range, but genotype-phenotype correlations are very complex, as shown in previous studies." (PMID 33807189, 2021). "In PCa, RB1 loss is rare in primary disease, but ADT may select for tumor loci with low RB1 activity to bypass cell-cycle blockage imposed by ADT." (PMID 34884545, 2021). "Focal MYCN amplification was present in four eyes (6.3%; Cases 3, 10, 31, and 48); the presence of MYCN amplification does not necessarily denote a MYCN-driven tumor which clearly Case 10 is not (germline RB1 mutation present)." (PMID 34283049, 2021). "MCPyV-negative MCCs commonly have loss-of-function RB1 mutation, and RB expression is undetectable in those MCC, whereas integration of MCPyV large T antigen in the RB promoter region is frequently found in MCPyV-positive tumor cells." (PMID 34359608, 2021). "Notably, tumor sample analysis showed that RB1 protein abundance was slightly increased, while protein levels of CDK6, cyclin D3, cyclin E1, cyclin D1, SKP2, and CDK2 were significantly decreased in the combination treatment group." (PMID 34508104, 2021).
tumor (continued). "RB1 loss, a common finding in advanced castration-resistant disease, was identified throughout mCRPC samples, but not in the primary tumor." (PMID 34568716, 2021). "CDKN1B, FOS, FOXO1, HDAC1, and RB1 were mainly expressed in the nuclear of tumor cells." (PMID 33748162, 2021). "In addition, RB1, a tumor suppressor which prevents cell proliferation by inhibiting E2F transcriptional activities, was negatively regulated by its phosphorylation." (PMID 34400640, 2021). "RB1 is a known tumor suppressor, which is frequently somatically deleted in CLL." (PMID 34622145, 2021). "RB1 promoter hypermethylation had previously been excluded in these tumours." (PMID 33670346, 2021). "Further, while RB1 (encoding Rb) status may be an important biomarker for CDK4/6 inhibitor sensitivity, some Rb-deficient tumour cells remain sensitive." (PMID 34784791, 2021). "This tumor carried wild-type RB1, which is essential for CDK4/6 inhibitor sensitivity." (PMID 33580196, 2021). "In this germline RB1 carrier, we showed that loss of the second allele was different in the two tumours and the lack of shared somatic mutations confirmed that the tumours had arisen independently." (PMID 33670346, 2021). "Other two Rb1 positive tumours revealed patchy staining pattern (10% and 20% of cells) for p16." (PMID 33737597, 2021). "In these neoplasms, p16 was reported to be induced by deregulation of RB1 as positive feedback." (PMID 32556556, 2021). "However, it is a weaker tumor suppressor when compared to RB1/p105, and its role as a tumor suppressor is often context-dependent." (PMID 34638509, 2021). "Among them, only one tumour showed diffuse strong positivity for both Rb1 and p16." (PMID 33737597, 2021). "The study identified a panel of genes which could predict RB1 status in both cultured cancer cell lines and clinical tumor samples." (PMID 33732631, 2021).
tumor (continued). "Interestingly, HIF1A behaves similarly to tumor suppressors such as RB1 in the normoxic and nutrient-rich conditions under which the screenings were carried out, with its knockout having a positive effect on cell viability." (PMID 33654095, 2021). "Identification of molecules mediating RB1 functions in controlling undifferentiated characters of tumor cells may endow us new tools to target cancer stem cells." (PMID 34359636, 2021). "RB1 is a well known tumor suppressor involved in CDK4/CDK6-dependent cell-cycle regulation." (PMID 34943047, 2021). "In 55% of cases, somatically-acquired RB1 mutations underpin tumourigenesis, are unilateral and do not incur predisposition to develop tumours at other sites." (PMID 33670346, 2021). "Type two is the deletion of the RB1 gene, a tumor suppressor gene located on chromosome 13." (PMID 34522485, 2021). "Namely, SBS03, and with this evidence for HRd exposure was not detectable in 5 of 10 tumours with RB1 mutation and HRd exposure had no significant linkage to RB1 mutational status." (PMID 34862364, 2021). "In addition, RB1 HD seem to have a lower impact in the cell populations in the tumor microenvironment, affecting only the endothelial cell population (lower scores)." (PMID 33879103, 2021). "The integrity of the RB1 C terminus is important for many activities of RB1, but whether or how any of these contribute to Rb1’s tumor suppressor activity is largely unknown." (PMID 34465025, 2021). "For most RB1 variants, observational data from other patients are not available, and, therefore, individualized prediction of tumor risk is not possible." (PMID 33807189, 2021). "Two papers recently highlighted the importance of other potential driver mutations including focal MYCN amplification, first reported in 1–2 % of tumours with no detectable RB1 mutations." (PMID 33670346, 2021). "We show that all Rb tumours in our cohort had at least one RB1 mutation, including three tumours where clinical testing was not able to confirm the existence of RB1 mutations." (PMID 33670346, 2021). "Regarding MYCN protein levels, the results suggest that knocking down MYCNOS1 mainly affected MYCN-amplified tumor cells without the RB1 mutation." (PMID 33270844, 2020). "We applied two different approaches: genotyping known RB1 mutations guided by the matched tumor, and de novo analysis without referring to knowledge from the tumor." (PMID 32633890, 2020). "Moreover, CDK4/6 inhibitors were found to increase tumor immunogenicity via RB1-dependent mechanisms." (PMID 32486375, 2020). "Rb/Rb1 inhibits cell cycle progression and functions as a tumor suppressor." (PMID 32419051, 2020). "In practice, tumor tissue is not always available for mutation discovery, requiring de novo identification of RB1 mutations from plasma cfDNA without prior knowledge." (PMID 32633890, 2020). "We postulated that this could be due to heterogeneity in RB1 expression across sub-populations of cells found in each patient-derived tumor culture." (PMID 32826891, 2020). "RB1 is a critical tumor suppressor in several types of cancer including HGSOC." (PMID 32591511, 2020). "It has been reported that RB1 functions as a tumor suppressor in the development of human cancers." (PMID 32013999, 2020).
tumor (continued). "High confident mutation discovery below 1% VAF will also be important for identifying mosaic RB1 mutations derived from sub‐population of the eyes that are absent in the tumor." (PMID 32633890, 2020). "The retinoblastoma gene (RB1) was the first tumor suppressor to be described." (PMID 31973216, 2020). "While RB1 was the first tumor suppressor gene identified, there are a large number of questions that remain relative to biological functions that could promote targeted therapeutic strategies for the treatment of cancer." (PMID 32242058, 2020). "RB1 is a tumor suppressor that is commonly disrupted in many human tumors, including breast cancer." (PMID 33489906, 2020). "Therefore, mutant RB1 became an important target for therapeutic exploitation for SCLC, despite its nature of tumor suppressor mutations." (PMID 33037191, 2020). "Rb1 appears to be a favorable factor that may be potentially used in the modulation of tumor-promoting APRIL expression." (PMID 33125603, 2020). "Collectively, concomitant deletion of Men1 and Rb1 accelerated tumor development in pancreas." (PMID 32733644, 2020). "Finally, we evaluated the anti-tumor efficacy of BAY-876 using a PDX model derived from a TNBC patient that expresses both RB1 and GLUT1." (PMID 32826891, 2020). "Without referring to RB1 status in the tumor, de novo mutation calling identified 7 of the 13 expected RB1 mutations (in 6 of 10 patients) with high confidence." (PMID 32633890, 2020). "The classical hypothesis is that biallelic loss of the RB1 gene results in the defective formation of the RB protein and triggers tumor initiation." (PMID 32366932, 2020). "Previous studies have shown that HELLS is regulated through the RB/E2F pathway and that loss of RB1 results in upregulation and overexpression of HELLS, a process that may contribute to epigenetic changes that drive tumor progression." (PMID 32071286, 2020). "RB1CC1 is a potential regulator of the tumor suppressor, RB1." (PMID 32920960, 2020). "Thus, there is a pressing clinical need to determine the factors responsible for tumor progression following RB1 inactivation in order to facilitate the development of new therapeutic strategies." (PMID 32426419, 2020). "Similarly to CCND1, expression of the cell cycle-related genes RB1 (retinoblastoma 1) and AR (androgen receptor) were also higher in luminal tumours relative to basal-like (see “AR” and “RB1”, P < 0.001 for luminal A vs. basal-like comparisons)." (PMID 30819233, 2019). "Interestingly, patient 8 had 1 tumor sample harboring only cell cycle deregulation through RB1 deletion confirming its major role in resistance to BRAF inhibitors." (PMID 30899440, 2019).